CRYAA (crystallin alpha A)
Description:
Contributes to the transparency and refractive index of the lens. In its oxidized form (absence of intramolecular disulfide bond), acts as a chaperone, preventing aggregation of various proteins under a wide range of stress conditions. Required for the correct formation of lens intermediate filaments as part of a complex composed of BFSP1, BFSP2 and CRYAA.
Synonyms: HspB4; CRYA1; CTRCT9
Tractability: PROTAC: a small molecule that binds it is known.
Gene: Protein-coding gene on chromosome 21 (43,169,008 to 43,172,810, forward strand). Ensembl gene ENSG00000160202.
Subcellular location: Cytoplasm; Nucleus
Subcellular location (Human Protein Atlas): Cytosol; Nucleoplasm
Gene Ontology:
Molecular function: identical protein binding; protein binding; structural molecule activity; structural constituent of eye lens
Biological process: negative regulation of apoptotic process; negative regulation of intracellular transport; protein stabilization; visual perception; lens development in camera-type eye; protein refolding; response to heat
Cellular component: cytoplasm; cytosol; nucleoplasm; nucleus; protein-containing complex
Homologues: Orthologues: chimpanzee CRYAA (100% identical), macaque CRYAA (98% identical), guinea pig CRYAA (95% identical), mouse Cryaa (95% identical), rabbit CRYAA (95% identical), rat Cryaa (95% identical), dog CRYAA (92% identical), pig CRYAA (92% identical), zebrafish cryaa (73% identical), tropical clawed frog cryaa (47% identical), Drosophila melanogaster l(2)efl (42% identical), Drosophila melanogaster Hsp67Ba (29% identical), and 14 more. Paralogues in human: CRYAB (54% identical), HSPB1 (40% identical), HSPB6 (38% identical), HSPB2 (33% identical), HSPB8 (26% identical), HSPB3 (23% identical), HSPB7 (21% identical), HSPB9 (19% identical).
Diseases named in the same sentence as CRYAA in open-access papers:
CRYAA is named in the same sentence as 34 diseases in open-access papers, as found by Europe PMC text mining. Sharing a sentence is not in itself a finding about the gene and the disease. The quoted sentences say what the papers report.
cataract (10 papers, 2009 to 2025). Partial or complete opacity of the crystalline lens of one or both eyes that decreases visual acuity and eventually results in blindness. "Of these, mutations in 9 crystallin genes have been associated with autosomal dominant cataracts (CRYAA, CRYAB, CRYBB1, CRYBB2, CRYBA1/A3, CRYBA4, CRYGC, CRYGD, and CRYGS) but only 3 with autosomal recessive cataracts (CRYAA, CRYBB1, and CRYBB3)." (PMID 19461930, 2009). "As much as 70% of autosomal dominant cataract may be accounted for by missense coding mutations in the genes for crystallins, particularly CRYAA, CRYBB2, and CRYGD, and connexins (GJA3, GJA8)." (PMID 21042563, 2010). "Previous studies have investigated the CRYAA gene in cataract patients from various countries worldwide." (PMID 37367076, 2023). "According to the PCR results and Western Blotting results, the lens of cataract group had lower expression levels of the CRYAA mRNA (p value: 0.0031) and protein expression (p value: 0.0117) compared to the normal group." (PMID 37253645, 2023). "Finally, variations in at least eight genes underlying genetic forms of cataract (EPHA2, GJA8, GALT, SLC16A12, HSF4, GALK1, FTL, and CRYAA), and at least 10 other diverse genes have been associated to varying degrees with age-related cataract." (PMID 21042563, 2010).
Age-related cataract (5 papers, 2010 to 2023). A type of cataract (opacification of the lens) that forms during the course of aging. "At least 8 genes are known to be directly associated with age-related cataracts, including EPHA2, GJA8, GALT, SLC16A12, HSF4, GALK1, FTL, and CRYAA." (PMID 36107580, 2022). "Age-related cataract (ARC) is the leading cause of visual impairment worldwide, and α-crystallin (CRYAA) is the predominant structural protein involved in the maintenance of lens clarity and refractive properties." (PMID 27507241, 2016).
retinal degeneration (2 papers, 2012 to 2024). Degeneration of the retina. "Understanding the regulatory mechanisms of CRYAA expression is necessary for developing strategies to modulate its expression or activity protecting against retinal degeneration induced by blue light exposure." (PMID 38997088, 2024). "In this study, we investigate the role of alpha-crystallin A (CRYAA) in neuro-retinal degeneration and their regulation by blue light." (PMID 38997088, 2024). "The precise mechanism of CRYAA involvement in the process of retinal degeneration is currently unknown." (PMID 22953002, 2012).
autoimmune uveitis (1 paper, 2015). An autoimmune form of uveitis (disease). "An elevation of retinal HSPB4/CRYAA expression that protects photoreceptors from degeneration has been reported in the early stages of experimental autoimmune uveitis." (PMID 26717306, 2015).
ocular hypertension (1 paper, 2020). Abnormally high intraocular pressure. "Like CRYAA and CRYBB, β-crystallin genes are downregulated at both transcriptional and protein levels in rat retinas with ocular hypertension, and upregulation of β-crystallins has been linked to retina neuroprotection and axonal regeneration." (PMID 32012756, 2020).
Type 1 diabetic (1 paper, 2022). "While our study did not specifically detect the post-translational modifications of MAM proteins, we were able to identify CRYAA as one of the differentially expressed proteins that comprises the MAM in Type 1 diabetic rat retina." (PMID 36139394, 2022).
tumor (3 papers, 2010 to 2018). "The Basal subtype showed the highest number of specific upregulated genes (DNAJC2, DNAJC6, HSPA5, HSPA14 and CRYAA), DNAJA3 and CCT2 were upregulated in Luminal B, and DNAJB3 was only upregulated in HER2 tumours." (PMID 29954368, 2018). "Two of the several proteins upregulated are alpha crystallin A (CRYAA) and peroxiredoxin 6 (PRDX6) which can inhibit apoptotic processes in tumor cells." (PMID 20844677, 2010).
cancer (2 papers, 2014 to 2025). A tumor composed of atypical neoplastic, often pleomorphic cells that invade other tissues. "In a similar vein, the activation of small heat shock proteins (CRYAA, CRYAB, CRYBB1), which are known as protectors against oxidative stress and apoptosis in normal and cancer cells, can be considered as a hallmark of generalized stress resistance." (PMID 41287033, 2025).
retinopathies (2 papers, 2022 to 2023). "CRYAA, a subunit of α-crystallin, is present in the normal retina; it participates in various retinopathies." (PMID 37025993, 2023). "Knock-out of CRYAA has been reported to inhibit ocular neovascularization in a murine model of oxygen-induced retinopathy, but more studies will be needed to establish a relation between CRYAA regulation and aflibercept treatment." (PMID 35684299, 2022).
CRYAA also shares sentences with these, for which no sentence is quoted: diabetes (4 papers); diabetic retinopathy (4); autosomal dominant cataract (3); Age-related nuclear cataract (1); aniridia (1); cardiomyopathy (1); Congenital aphakia (1); congenital cataracts (1); cystic fibrosis (1); Down syndrome (1); dry eye (1); glaucoma (1); holoprosencephaly (1); inflammation (1); lung carcinoma (1); macular degeneration (1); metabolic disorders (1); Microcornea (1); microphthalmia (1); multiple sclerosis (1); myopathies (1); nuclear cataract (1); pancreatic cancer (1); retinoblastoma (1); sebaceous adenocarcinoma (1).